CFTR (CF transmembrane conductance regulator)
Description:
Epithelial ion channel that plays an important role in the regulation of epithelial ion and water transport and fluid homeostasis. Mediates the transport of chloride ions across the cell membrane. Possesses an intrinsic ATPase activity and utilizes ATP to gate its channel; the passive flow of anions through the channel is gated by cycles of ATP binding and hydrolysis by the ATP-binding domains. The ion channel is also permeable to HCO(3)(-); selectivity depends on the extracellular chloride concentration. In vitro, mediates ATP-dependent glutathione flux. Exerts its function also by modulating the activity of other ion channels and transporters. Plays an important role in airway fluid homeostasis. Contributes to the regulation of the pH and the ion content of the airway surface fluid layer and thereby plays an important role in defense against pathogens. Modulates the activity of the epithelial sodium channel (ENaC) complex, in part by regulating the cell surface expression of the ENaC complex. Inhibits the activity of the ENaC channel containing subunits SCNN1A, SCNN1B and SCNN1G. Inhibits the activity of the ENaC channel containing subunits SCNN1D, SCNN1B and SCNN1G, but not of the ENaC channel containing subunits SCNN1A, SCNN1B and SCNN1G. May regulate bicarbonate secretion and salvage in epithelial cells by regulating the transporter SLC4A7. Can inhibit the chloride channel activity of ANO1. Plays a role in the chloride and bicarbonate homeostasis during sperm epididymal maturation and capacitation.
Synonyms: ABCC7; MRP7; ABC35; TNR-CFTR; dJ760C5.1; CFTR/MRP; CF
Tractability: Small molecule: an approved drug acts on it; a structure with a bound ligand is known; a high-quality ligand is known; it has a high-quality binding pocket; it belongs to a druggable protein family. Antibody: UniProt places it where antibodies can reach, with high confidence; its Gene Ontology location is reachable by antibodies, with high confidence; UniProt predicts a signal peptide or a membrane-spanning region. PROTAC: UniProt records ubiquitination sites on it; ubiquitination databases record sites on it; a small molecule that binds it is known.
Target class: Chloride channel; Cystic fibrosis transmembrane conductance regulator; Ion channel; Other ion channel
Chemical probes: A-1596586 (high quality), ICENTICAFTOR (high quality)
Safety:
Unwanted effects reported when the protein is acted on. In parentheses: how it was acted on, where the effect was seen, and who reports it.
adverse events (source: ClinPGx)
Gene: Protein-coding gene on chromosome 7 (117,287,120 to 117,715,971, forward strand). Ensembl gene ENSG00000001626.
Subcellular location: Apical cell membrane; Early endosome membrane; Cell membrane; Recycling endosome membrane; Endoplasmic reticulum membrane; Nucleus
Pathways (Reactome):
Autophagy: Aggrephagy; Chaperone Mediated Autophagy; Late endosomal microautophagy
Signal Transduction: RHO GTPases regulate CFTR trafficking; RHOQ GTPase cycle
Vesicle-mediated transport: Cargo recognition for clathrin-mediated endocytosis; Clathrin-mediated endocytosis
Developmental Biology: Developmental Lineage of Pancreatic Ductal Cells
Disease: Defective CFTR causes cystic fibrosis
Metabolism of proteins: Ub-specific processing proteases
Transport of small molecules: ABC-family protein mediated transport
Gene Ontology:
Molecular function: 14-3-3 protein binding; ATP hydrolysis activity; bicarbonate transmembrane transporter activity; chloride channel activity; chloride channel inhibitor activity; enzyme binding; intracellularly ATP-gated chloride channel activity; PDZ domain binding; protein binding; protein-folding chaperone binding; Sec61 translocon complex binding; ATP binding; ATPase-coupled transmembrane transporter activity; chloride channel regulator activity; chloride transmembrane transporter activity; ABC-type transporter activity
Biological process: bicarbonate transport; cellular response to forskolin; chloride transmembrane transport; multicellular organismal-level water homeostasis; response to endoplasmic reticulum stress; transepithelial water transport; amelogenesis; cellular response to cAMP; intracellular pH elevation; membrane hyperpolarization; positive regulation of enamel mineralization; sperm capacitation; transmembrane transport; water transport; chloride transport; monoatomic ion transmembrane transport; monoatomic ion transport
Cellular component: apical plasma membrane; cell surface; cytoplasm; cytosol; early endosome; early endosome membrane; endoplasmic reticulum membrane; membrane; plasma membrane; protein-containing complex; recycling endosome; basolateral plasma membrane; clathrin-coated endocytic vesicle membrane; endosome membrane; Golgi-associated vesicle membrane; lysosomal membrane; nucleus; recycling endosome membrane
Genetic constraint (gnomAD): Loss-of-function variants: 116 observed, 117.45 expected, observed/expected ratio (o/e) 0.99, 90% interval 0.85 to 1.15. The upper end of that interval is the gene's LOEUF score, 1.15, which puts it in group 5 of 6, group 1 being the genes least tolerant of losing a copy. Missense variants: 1,523 observed, 1,412.5 expected, observed/expected ratio (o/e) 1.08, 90% interval 1.03 to 1.12. Synonymous variants: 476 observed, 511.79 expected, observed/expected ratio (o/e) 0.93, 90% interval 0.86 to 1.
Gene-disease validity (ClinGen):
ClinGen rates the evidence that CFTR causes each of these diseases.
cystic fibrosis (autosomal recessive): Definitive. Autosomal recessive disorder caused by pathogenic variants in the CFTR gene (cystic fibrosis transmembrane conductance regulator), which encodes a chloride and bicarbonate channel expressed in epithelial cells, and follow the diagnosis criteria.
Homologues: Orthologues: chimpanzee CFTR (99% identical), macaque CFTR (97% identical), pig CFTR (92% identical), rabbit CFTR (92% identical), dog CFTR (90% identical), guinea pig CFTR (88% identical), mouse Cftr (79% identical), rat Cftr (78% identical), tropical clawed frog cftr (78% identical), zebrafish cftr (56% identical), Drosophila melanogaster Mrp5 (25% identical), Drosophila melanogaster CG9270 (25% identical), and 9 more. Paralogues in human: ABCC4 (30% identical), ABCC2 (25% identical), ABCC1 (24% identical), ABCC11 (24% identical), ABCC3 (24% identical), ABCC9 (23% identical), ABCC5 (23% identical), ABCC6 (23% identical), ABCC12 (23% identical), ABCC8 (23% identical), ABCC10 (22% identical).
Diseases named in the same sentence as CFTR in open-access papers:
CFTR is named in the same sentence as 553 diseases in open-access papers, as found by Europe PMC text mining. Sharing a sentence is not in itself a finding about the gene and the disease. The quoted sentences say what the papers report.
cystic fibrosis (3,555 papers, 1998 to 2026). "Cystic fibrosis is a monogenic genetic disease caused by mutations in the Cystic Fibrosis Transmembrane conductance Regulator (CFTR) chloride/bicarbonate channel, which is expressed in certain epithelial cells." (PMID 41701793, 2026). "Dysfunction of the CFTR (cystic fibrosis transmembrane conductance regulator) protein is associated with an increased risk of GI tumors, both in patients with cystic fibrosis and in sporadic GI cancers." (PMID 41601884, 2026). "W1282X CFTR is the most prevalent CF-causing variantamong cysticfibrosis patients of Ashkenazi descent and a mutational defect forwhich targeted drug therapy is not available." (PMID 41386645, 2026). "Mutations in the cystic fibrosis transmembrane conductance regulator (CFTR) gene, which encodes a cAMP-activated chloride channel, cause cystic fibrosis, the most common life-threatening inherited disorder among White individuals." (PMID 41869727, 2026). "CFTR mutations cause cystic fibrosis; the two common mutations, ΔF508 and G551D, reportedly also impair channel activation by PKA." (PMID 41920076, 2026). "CFTR dysfunction in mucoviscidosis and CFTR null mice is associated with goblet cell hyperplasia, defective mucin degranulation, and the presence of viscid mucus on the epithelial surface." (PMID 41498431, 2026). "Brazil was the first Latin American country to make ivacaftor available in the public health system for cystic fibrosis patients older than 6 years having one of nine class III CFTR variants, or patients older than 18 years with an R117H causing variant." (PMID 41016862, 2026). "Biallelic GVs in the CFTR gene encoding an ATP-binding cassette transporter that functions as a chloride channel cause cystic fibrosis mainly affecting the lung, gastrointestinal tract, and skin." (PMID 41546701, 2026). "Six carrier couples (4%) were identified as being at reproductive risk of non-syndromic hearing loss (GJB2, 2 couples), cystic fibrosis (CFTR), Stargardt disease and retinitis pigmentosa (ABCA4), Smith-Lemli-Opitz syndrome (DHCR7), and Fabry disease (GLA)." (PMID 42071123, 2026). "Mutations in the cystic fibrosis transmembrane conductance regulator (CFTR) cause cystic fibrosis, an autosomal recessive multiorgan disorder." (PMID 42080975, 2026). "We also used rectal organoids established from a cystic fibrosis patient with a homozygous Δ508F mutation to model CFTR deficiency." (PMID 41498431, 2026). "Cystic fibrosis is characterised by variants in the CFTR gene that lead to impaired epithelial chloride-ion transport and increased mucus viscosity." (PMID 41752197, 2026). "Human colonic and rectal organoids from healthy controls and cystic fibrosis patients with F508del mutations were studied in the proliferative state with high endogenous CFTR expression and inducible SLC26A3 overexpression." (PMID 41498431, 2026). "Cystic fibrosis is a life-shortening disease caused by variants in the cystic fibrosis transmembrane conductance regulator (CFTR) gene." (PMID 39811546, 2025). "Cystic fibrosis is a multisystem disorder caused by mutations in the CFTR gene that lead to impaired ion and fluid transport across secretory epithelia." (PMID 40868962, 2025). "Cystic Fibrosis is an autosomal recessive disease caused by mutations in the CFTR gene leading to thickening of mucus, nasal polyps, and predisposing airway infections." (PMID 40398368, 2025). "Further eleven selected variants in CFTR commonly associated with cystic fibrosis in Caucasian and African populations, were explored, and a single marker (rs115545701) was found to be carried by only one participant (MAF = 0.005)." (PMID 40376268, 2025). "MassARRAY has been evaluated for screening of SMA, detection of CFTR causing variants in previously genotyped cystic fibrosis patients and in patients with non-syndromic hearing loss and Fabry disease." (PMID 41283366, 2025).
cystic fibrosis (continued). "Cystic fibrosis is a life limiting autosomal genetic disease caused by bi-allelic mutations within the Cystic Fibrosis Transmembrane Conductance Regulator (CFTR) gene." (PMID 41235117, 2025). "Cystic fibrosis is an autosomal recessive disease caused by mutations in the cystic fibrosis transmembrane conductance regulator (CFTR) gene, a channel protein responsible for regulating ion transport across cell membranes." (PMID 40006567, 2025). "For example, certain biallelic variants of the cystic fibrosis transmembrane conductance regulator (CFTR) are sufficient to cause cystic fibrosis, an autosomal recessive disease." (PMID 40282361, 2025). "Cystic Fibrosis is a genetic disorder caused by mutations in the CF Transmembrane Conductance Regulator (CFTR) gene." (PMID 40807208, 2025). "Cystic fibrosis is a genetic disorder caused by mutations in the CFTR gene, leading to defective ion transport and impaired function of various organs." (PMID 40563468, 2025). "Cystic fibrosis is a multisystemic disorder caused by mutations in the CFTR gene, leading to defective chloride and bicarbonate transport across epithelial surfaces." (PMID 40868962, 2025). "Cystic fibrosis is a rare genetic disorder caused by a series of variants that affect the function of the CFTR gene, which encodes the CFTR protein." (PMID 40553696, 2025). "Cystic fibrosis is a life-limiting autosomal recessive disorder caused by mutations in the cystic fibrosis transmembrane conductance regulator (CFTR) gene, resulting in progressive lung disease, pancreatic insufficiency, and multisystem complications." (PMID 41357806, 2025). "Cystic fibrosis is caused by mutations in the gene encoding for the CF transmembrane conductance regulator (CFTR) protein." (PMID 40753522, 2025). "Cystic fibrosis is a multi-organ disease caused by dysfunction of the cystic fibrosis transmembrane conductance regulator (CFTR) protein." (PMID 39756424, 2025). "Cystic fibrosis is an autosomal recessive disease resulting from mutations in the gene that encodes the Cystic Fibrosis Transmembrane Conductance Regulator (CFTR) protein." (PMID 41380738, 2025). "The c.1375_1383del variant is a rare CFTR variant and is associated with early, clinically significant manifestations of cystic fibrosis in infants, which necessitates early recognition and aggressive management to improve patient outcomes." (PMID 40933696, 2025). "Cystic fibrosis is an inherited genetic disease caused by dysregulation of the cystic fibrosis transmembrane regulator (CFTR) gene, a chronic hyperinflammatory state and frequently occurring severe bacterial infections of the lungs." (PMID 41226119, 2025). "Cystic fibrosis is an autosomal recessive monogenic disorder arising due to mutations in the cystic fibrosis transmembrane conductance regulator (CFTR) gene, which encodes a cAMP-dependent chloride ion channel." (PMID 40565081, 2025). "Cystic fibrosis is caused by mutations in the cystic fibrosis transmembrane conductance regulator (CFTR) gene, which encodes a chloride ion channel, and occurs frequently in the Caucasian population but rarely in Asia." (PMID 40718166, 2025). "Cystic fibrosis is most commonly caused by the ΔF508 mutation in the CFTR gene, leading to misfolding and degradation of the CFTR protein." (PMID 41323797, 2025). "This mutation leads to a pseudo-exon containing a premature stop codon, resulting in CFTR deficiency and cystic fibrosis." (PMID 41022769, 2025). "Cholesterol interaction with the membrane-embedded portion of the CFTR protein and alterations in cholesterol metabolism have been previously shown for variants causing cystic fibrosis." (PMID 40428425, 2025). "Cystic fibrosis is an autosomal recessive disease caused by pathogenic variants in the cystic fibrosis transmembrane conductance regulator (CFTR) gene." (PMID 39859153, 2025).
cystic fibrosis (continued). "Cystic fibrosis disease is a recessively inherited genetic disorder of the cystic fibrosis transmembrane conductance regulator (CFTR) gene which encodes an anion channel." (PMID 40192756, 2025). "Cystic fibrosis is an autosomal recessive condition that is caused by loss-of-function mutations in the CF transmembrane conductance regulator (CFTR) gene." (PMID 40013020, 2025). "Cystic fibrosis is a hereditary disorder caused by mutations in the gene encoding the CF transmembrane conductance regulator (CFTR), impairing its function and leading to a build-up of viscous mucus in many organs, including the lungs, gut and pancreas." (PMID 39836539, 2025). "Cystic fibrosis is a complex multiorgan autosomal recessive disease caused by genetic variants in the cystic fibrosis transmembrane conductance regulator (CFTR) gene." (PMID 40868904, 2025). "A genetic DNA test revealed mutations in both alleles of the CFTR gene, confirming the F508del genotype for cystic fibrosis." (PMID 40364218, 2025). "Cystic fibrosis is a rare hereditary genetic disease caused by defects in the cystic fibrosis transmembrane conductance regulator (CFTR) protein, which is involved in the regulation of hydro‐electrolyte exchange." (PMID 40176392, 2025). "Cystic fibrosis is an autosomal recessive disorder caused by loss-of-function mutations in the CF transmembrane conductance regulator (CFTR) gene, which encodes a chloride and bicarbonate channel." (PMID 39949461, 2025). "This study assessed the effect of CFTR pathogenic variant status, detected during prenatal carrier screening, for the incidence and clinical recognition of cystic fibrosis‐related phenotypes." (PMID 40468859, 2025). "The chaperoning effects of glycerol were previously observed for ER‐trapped cystic fibrosis variants of the CFTR." (PMID 40485335, 2025). "Cystic fibrosis is a genetic disorder caused by mutations in the CFTR gene, which result in multiple alterations in the intestinal environment, including thick mucus secretion, reduced intestinal pH, chronic inflammation, and microbial imbalance." (PMID 41374046, 2025). "We included studies that used any CFTR modulators (monotherapy or combination) for the treatment of children and adults with a confirmed diagnosis of cystic fibrosis with phe508del CFTR mutation." (PMID 41377908, 2025). "The combined expression of the wild-type transporter with the variant does not appear to increase the half-life of the wild-type, unlike what is observed in other loss-of-function mutants of different transporters, such as CFTR in cystic fibrosis." (PMID 40725001, 2025). "Cystic Fibrosis is a progressive genetic disease resulting from cystic fibrosis transmembrane conductance regulator (CFTR) gene mutations and impacting more than 70,000 people globally." (PMID 38980550, 2025). "Cystic fibrosis is classified among a group of autosomal recessive genetic disorders resulting from mutations in the Cystic Fibrosis Transmembrane Conductance Regulator (CFTR) gene, located on the long arm of chromosome 7 (7q31)." (PMID 41009994, 2025). "The main cause of cystic fibrosis in European and Russian populations is the F508del pathogenic variant in the CFTR gene." (PMID 40869263, 2025). "Polycystic liver disease, also known as cystic fibrosis, caused by mutations in a cell-surface chloride transporter called cystic fibrosis transmembrane regulator (CFTR) gene." (PMID 40008122, 2025). "Lastly, patients with pancreas-sufficient cystic fibrosis are at risk of acute pancreatitis, which can be reduced by cystic fibrosis transmembrane conductance regulator (CFTR) modulator therapy, such as with Ivacaftor or Tezacaftor." (PMID 39941188, 2025). "Cystic fibrosis is a recessive genetic disorder caused by mutations in the cystic fibrosis transmembrane conductance regulator (CFTR) gene." (PMID 40563468, 2025).